ARFGAP3 (ARF GTPase activating protein 3)
Description:
GTPase-activating protein (GAP) for ADP ribosylation factor 1 (ARF1). Hydrolysis of ARF1-bound GTP may lead to dissociation of coatomer from Golgi-derived membranes to allow fusion with target membranes.
Synonyms: ARFGAP1
Tractability: Antibody: UniProt places it where antibodies can reach, with high confidence. PROTAC: ubiquitination databases record sites on it; its protein half-life has been measured.
Gene: Protein-coding gene on chromosome 22 (42,796,502 to 42,858,106, reverse strand). Ensembl gene ENSG00000242247.
Subcellular location: Cytoplasm; Golgi apparatus membrane
Subcellular location (Human Protein Atlas): Cytosol; Golgi apparatus
Pathways (Reactome):
Signal Transduction: CDC42 GTPase cycle; RHOG GTPase cycle
Vesicle-mediated transport: COPI-dependent Golgi-to-ER retrograde traffic; COPI-mediated anterograde transport
Gene Ontology:
Molecular function: GTPase activator activity; protein binding
Biological process: COPI coating of Golgi vesicle; protein secretion; retrograde vesicle-mediated transport, Golgi to endoplasmic reticulum; intracellular protein transport; vesicle-mediated transport
Cellular component: cytosol; Golgi apparatus; Golgi membrane; membrane; cytoplasm
Genetic constraint (gnomAD): Loss-of-function variants: 53 observed, 59.68 expected, observed/expected ratio (o/e) 0.89, 90% interval 0.71 to 1.12. The upper end of that interval is the gene's LOEUF score, 1.12, which puts it in group 4 of 6, group 1 being the genes least tolerant of losing a copy. Missense variants: 514 observed, 533.42 expected, observed/expected ratio (o/e) 0.96, 90% interval 0.9 to 1.04. Synonymous variants: 169 observed, 178.65 expected, observed/expected ratio (o/e) 0.95, 90% interval 0.83 to 1.08.
Homologues: Orthologues: chimpanzee ARFGAP3 (99% identical), macaque ARFGAP3 (96% identical), dog ARFGAP3 (89% identical), pig ARFGAP3 (85% identical), mouse Arfgap3 (81% identical), rat Arfgap3 (81% identical), guinea pig ARFGAP3 (66% identical), tropical clawed frog arfgap3 (66% identical), zebrafish arfgap3 (49% identical). Paralogues in human: ARFGAP2 (55% identical), ARFGAP1 (22% identical), ARAP2 (21% identical), ARAP1 (20% identical), ASAP1 (19% identical), ARAP3 (19% identical), ASAP2 (19% identical), ASAP3 (16% identical), ACAP3 (15% identical), ACAP2 (15% identical), ADAP1 (14% identical), ACAP1 (13% identical), and 16 more.
Diseases named in the same sentence as ARFGAP3 in open-access papers:
ARFGAP3 is named in the same sentence as 4 diseases in open-access papers, as found by Europe PMC text mining. Sharing a sentence is not in itself a finding about the gene and the disease. The quoted sentences say what the papers report.
prostate carcinoma (2 papers, 2016 to 2019). A carcinoma that arises from epithelial cells of the prostate gland. "Gene combinations of OBSCN, FAM83H, CLDN7 and ARFGAP3 significantly predicted the risk of re-occurrence after treatment, demonstrating that the genes identified through this screen can have high predictive value in patients and thus are potential prostate cancer biomarkers." (PMID 27792127, 2016). "For instance, ARFGAP3 is detected to be able to facilitate the proliferation and migration of prostate cancer cells." (PMID 31386624, 2019).
pelvic organ prolapse (1 paper, 2021). Abnormal descent of a pelvic organ resulting in the protrusion of the organ beyond its normal anatomical confines. "The purpose of this study was to study the expression of adenosine diphosphate ribosylation factor GTPase-activating protein 3 (ArfGAP3) in the anterior vaginal wall of patients with pelvic organ prolapse (POP)." (PMID 31868832, 2021).
cancer (2 papers, 2014 to 2025). A tumor composed of atypical neoplastic, often pleomorphic cells that invade other tissues. "Pathway analysis for rituximab-resistant cell lines showed enriched proteins (CYTH1, SEC24D, VPS25, and ARFGAP3) involved in membrane trafficking, which is a pathway mediating many processes and enzyme functions that cancer cells can use to promote tumorigenesis and drug responses." (PMID 41301803, 2025). "For modules M3, M4, and M5, although the corresponding GO_BP terms were not directly related to cancer, we found PrCa-relevant genes in these three modules, including BTG2, FOS (also known as c-Fos), and CXCR4 in module M3; ARFGAP3 and CDH1 in module M4; and SMAD3 and MXI1 in module M5." (PMID 25418933, 2014).
ARFGAP3 also shares sentences with these, for which no sentence is quoted: tumor (1 paper).